IL18 (interleukin 18)
Diseases named in the same sentence as IL18 in open-access papers (continued):
Sharing a sentence is not in itself a finding about the gene and the disease.
psoriasis (continued). "Despite there being much ground to cover, accumulating evidence highlights the involvement of IL-18 and IL-37 in the pathogenesis of inflammatory diseases such as AD and psoriasis." (PMID 39126010, 2024). "CD161 serves as a marker for NK cells that can respond to IL-12 and IL-18 during differentiation, leading to the subsequent upregulation of NKp30, CD160, CD25, CD69, and IFN-γ—an identified psoriasis-associated pathogenic factor." (PMID 38596682, 2024). "To date, many reports reveal the dysregulation of IL-18 in several skin pathologies, e.g., psoriasis, atopic dermatitis, rosacea, and bullous pemphigoid." (PMID 39769266, 2024). "Overexpression of TNF-α results in excessive production of proinflammatory cytokines like IL-6, IL-8, IL-12, and IL-18, driving a transformation of the psoriasis phenotype to pustular psoriasis." (PMID 38695018, 2024). "Compared to healthy controls, patients with psoriasis exhibit higher levels of IL-18 both in lesions and in blood and the levels correlate with disease severity." (PMID 39769266, 2024). "Serum levels of several proinflammatory cytokines, including TNF-α,IFN-γ,IL-6,IL-8,IL-12,IL-17A and IL-18 were elevated in individuals diagnosed with psoriasis compared to healthy controls, suggesting that psoriasis develops systemically." (PMID 38504983, 2024). "This review highlights the complex involvement of IL-18 and IL-37 in the immune innate and adaptative systems and their roles in AD and psoriasis." (PMID 39126010, 2024). "A psoriasis-like mouse model in which an IL-18-neutralizing antibody successfully blocked the harmful Th17 immune response confirmed that indeed, IL-18 is a player in psoriasis." (PMID 39769266, 2024). "Elevated levels of IL-18 have been detected in both the serum and lesional skin of individuals with psoriasis compared to healthy controls." (PMID 39126010, 2024). "Conversely, IL-18-focused treatments have demonstrated promise in adult-onset Still’s Disease, warranting further exploration for their potential efficacy in psoriasis and atopic dermatitis." (PMID 39126010, 2024). "In a mouse model of imiquimod-induced psoriasis, IL-18 exacerbated inflammation and contributed to micro-abscess formation of scale development by upregulating pro-inflammatory cytokines and reducing anti-inflammatory cytokines." (PMID 39126010, 2024). "Recombinant human IL-18 binding protein, which neutralize IL-18 along with IL-37 had more success in experiments and clinical trials in psoriasis, rheumatoid arthritis, hemophagocytic lymphohistiocytosis, and adult onset Still disease." (PMID 37744367, 2023). "The pro-inflammatory mediators associated with psoriasis are IL1B, IL2, IL6, IL12, IL15, IL17, IL18, and IL20." (PMID 37569685, 2023). "Further, IL-18 can be secreted by keratinocytes and is involved in psoriasis development, which is in line with our findings." (PMID 37883350, 2023). "Previous studies have demonstrated elevated levels of circulating factor IL-18 in the serum of individuals with psoriasis." (PMID 37883350, 2023). "Patients with psoriasis had significantly higher levels of IL-18 in the lesions and in the serum compared to healthy controls." (PMID 36742296, 2023). "This is in accordance with a former study that showed a correlation between serum levels of IFN-γ, TNFα, IL-18 and IL-12 and psoriasis severity." (PMID 37049538, 2023). "We herein induced psoriasis in Il18ra-deficient (Il18rα−/−) and wild-type (WT) mice using IMQ to investigate the role of the IL-18/IL-18Rα signaling pathway in pathogenesis and severity of psoriasis." (PMID 37964882, 2023). "According to the ROC curve, most gene expression were significantly correlated with the occurrence of psoriasis, except IL18." (PMID 37861483, 2023). "According to ROC, most expression these PDGs were significantly related with the occurrence of psoriasis, except IL18." (PMID 37861483, 2023).
psoriasis (continued). "The AUC values of most genes were >0.8 in the 3 datasets apart from IL-18, demonstrating they were accurate and specific in differentiating psoriasis cases from healthy samples." (PMID 37861483, 2023). "Corresponding with findings of lesional skin, peripheral blood levels of ASC, IL-1β and IL-18 were found increased in untreated psoriasis patients compared to healthy controls." (PMID 37325658, 2023). "Whereas most research focused on one or two PRGs in vivo or vitro, for instance, the pathogenesis of psoriasis is closely related to caspase-1, IL-1β, IL-18, or GSDMD." (PMID 36110207, 2022). "Many in vitro studies, animal models, and some clinical studies support the vital role of IL-18 in Psoriasis, MG, and other diseases." (PMID 36032110, 2022). "Several studies have strongly indicated that IL-18 is a strong biomarker for clinical psoriasis symptoms." (PMID 36032110, 2022). "Overexpression of IL-18 has been detected in both skin lesions and peripheral blood of psoriasis patients, with IL-18 serum levels directly correlating with psoriasis severity." (PMID 36012744, 2022). "IL-18 levels are usually elevated in psoriasis, systemic lupus erythematosus (SLE), hypertension, chronic kidney disease, multiple sclerosis (MS) patients and Coronavirus disease 2019 (COVID-19) which correlates with caspase-1 levels." (PMID 36032110, 2022). "In a mouse model, IL-18 also induced prominent inflammation, with increased expression of IFNγ and enhancement of psoriasis-like epidermal hyperplasia." (PMID 36012744, 2022). "In an IL-18 knockout mouse model of psoriasis induced by Imiquimod (IMQ), IMQ induced mice manifested larger areas of Munro micro abscesses and had upregulated expression of IL-1β, IL-4, and IL-27 compared to wild type (WT)." (PMID 36032110, 2022). "T cells from psoriasis patients expressed higher levels of GADD45b after stimulation with a mixture of IL-12 and IL-18 compared to controls." (PMID 34272424, 2021). "The ROC area for IL-18 was 0.77 (95%, C.I: 0.66–0.85), with a sensitivity and specificity of 73.81% and 64.10% for the diagnosis of psoriasis, respectively." (PMID 34685372, 2021). "Psoriasis patients who were asymptomatic for SARS-COV-2 exhibited immune imbalance with high levels of IL-18, IL-17A and IL-6, and low levels of IL-27 compared to healthy controls." (PMID 34068473, 2021). "While strong epidermal hyperplasia and prominent Th1 inflammatory responses have been reported in psoriasis-like skin models, few studies have explored the in vivo concentrations of IL18 in psoriatic patients." (PMID 34685372, 2021). "Its expression was also reduced after dermatological treatment, reinforcing the participation of IL-18 in psoriasis pathogenesis." (PMID 34685372, 2021). "Psoriasis patients exhibit enhanced circulating levels of IL-6, IL-18, IL-17A, IFN-γ, TNF, IL-1β, IL-27 and IL-29." (PMID 34068473, 2021). "Interleukin (IL) -1 and IL-18 are proinflammatory cytokines belonging to the IL-1 family, which is one of the key players in the development of psoriasis." (PMID 34685372, 2021). "Their findings indicate that inflammasome signaling pathway proteins, such as IL-18 and ASC, play a crucial role in inflammatory responses associated with psoriasis pathology." (PMID 34072753, 2021). "The authors found significantly higher levels of IFN-γ, TNF-α, IL-6, IL-8, IL-12, and IL-18 in patients with psoriasis." (PMID 29619128, 2018). "The pooled serum levels of TNF-α, IFN-γ, IL-2, IL-6, IL-8, IL-18, IL-22, chemerin, lipocalin-2, resistin, sE-selectin, fibrinogen and C3 were higher in psoriasis patients compared with healthy controls (all P < 0.05)." (PMID 29416693, 2018). "Serum levels of TNF-α, IFN-γ, IL-2, IL-6, IL-8, IL-18, IL-22, chemerin, lipocalin-2, resistin, sE-selectin, fibrinogen, complement 3, and adiponectin correlate with psoriasis and can be used as potential biomarkers for psoriasis and response to the treatment." (PMID 29416693, 2018).
psoriasis (continued). "As for IL-18, IL-18R is also expressed in lesion skin of chronic inflammatory diseases such as psoriasis and cutaneous lupus erythematosus." (PMID 28839348, 2017). "IL-18 is a potent proinflammatory cytokine involved in chronic inflammatory conditions such as cutaneous lupus erythematosus, psoriasis, and atopic dermatitis." (PMID 28839348, 2017). "In fact, IL-18 levels are significantly higher in skin lesions of psoriasis patients relative to healthy controls." (PMID 27941650, 2016). "In fact, increased expression of IL-18 and its receptor were observed on lesional skin tissues from patients diagnosed with inflammatory cutaneous diseases such as psoriasis, rosacea, atopic dermatitis, or alopecia areata." (PMID 27941650, 2016). "In conclusion, these results indicate that studying the changes in the expression of IL-18 will be helpful to further understand of the pathogenesis of psoriasis." (PMID 26690141, 2015). "Several human diseases, such as systemic lupus erythematosus, rheumatoid arthritis, Crohn's disease, psoriasis and graft-versus-host-disease are thought to be mediated in part by IL-18." (PMID 24926998, 2014). "Certainly validated animal models support a role for IL-18 in acute renal injury, psoriasis, heart failure, MAS, and inflammatory bowel disease." (PMID 24115947, 2013). "Diseases such as systemic lupus erythematosus, rheumatoid arthritis, Type-1 diabetes, Crohn’s disease, psoriasis, and graft versus host disease are thought to be mediated, in part, by IL-18." (PMID 24115947, 2013). "A number of publication have described that high levels of IL-18 and/or IL-18R are expressed in lesional skin of chronic inflammatory diseases such as psoriasis and cutaneous lupus erythematosus (CLE)." (PMID 22761702, 2012). "IL-18 is highly expressed in chronic phases of skin diseases such as eczema, lupus erythematosus and psoriasis but also in e.g. lupus nephritis, chronic joint diseases and graft-versus-host disease." (PMID 22761702, 2012). "IL-18 is an important mediator involved in chronic inflammatory conditions such as cutaneous lupus erythematosus, psoriasis and chronic eczema." (PMID 22761702, 2012). "The up-regulation of IL-18 in suprabasal keratinocytes in skin lesions has been described in psoriasis." (PMID 21765951, 2011). "The lymphocyte associated regions containing HLA-B and HLA-C, harbors two genes that have been implicated in multiple GWAS as modifiers of immunological responses, associated with IL-18 levels, HIV-1 control, vitiligo, multiple clerosis, and psoriasis." (PMID 21738480, 2011). "The mean plasma level of IL-18 was significantly increased inmales with psoriasis as compared to the healthy control male group(P = .027)." (PMID 17611614, 2007). "Inconclusion, based on the increased IL-18 levels in plasma of ourpatients, this cytokine seems to play a role in theetiopathogenesis of psoriasis which was already suggested by manyauthors." (PMID 17611614, 2007). "Interleukin-18 is a cytokine potentially involved in the pathogenesis of psoriasis." (PMID 40731810, 2025). "In our study, we demonstrate for the first time that lower baseline serum IL-18 levels in patients with psoriasis may predict an excellent clinical response to biologic therapy with secukinumab, defined as complete skin clearance (PASI = 0) at three months." (PMID 40650209, 2025). "Previous studies have indicated that pyroptosis in psoriasis triggers caspase-1 activation, increases IL-1β and IL-18 expression, and activates the IL-23/Th17 pathway, leading to the secretion of large amounts of inflammatory cytokines and chemokines, which ultimately induces skin inflammation." (PMID 40722833, 2025). "Furthermore, the IL-18 in the patient sample was significantly elevated, along with IL-17A and IL-17F compared with HS and psoriasis samples previously analyzed." (PMID 39834723, 2025).
psoriasis (continued). "Incorporating IL-13, IL-18, and their ratio into clinical algorithms may facilitate precision-guided biologic therapy in psoriasis." (PMID 40650209, 2025). "Both IL-18 and IL-37 have shown abnormal expression levels in various inflammatory and autoimmune disorders, including skin diseases such as atopic dermatitis (AD) and psoriasis." (PMID 39126010, 2024). "IL-1β promotes the differentiation of Th17 cells to secrete IFN-γ, and IL-18 enhances IFN-γ-induced production of C-X-C motif chemokine 9 (CXCL9), CXCL10 and CXCL11, which migrate from dermis to epidermis causing chronic inflammatory activation of psoriasis." (PMID 39689159, 2024). "However, in 2021–2022, psoriasis entered the top 50 for the first time, indicating that IL‐18 research and psoriasis have gradually increased in recent years, and their popularity is on the rise." (PMID 39188114, 2024). "We found that in the skin of psoriasis-like mice, Il1b and Il6 were mainly expressed in neutrophils, while Il17a was mainly expressed in T cells, Il18 was mainly expressed in macrophages and fibroblasts, and Tnfa was mainly expressed in macrophages and T cells." (PMID 39717896, 2024). "Furthermore, assessing the levels of S100A8, IL-18, and sE-selectin in saliva can also be useful, as these are potential biomarkers for diagnosing psoriasis." (PMID 39595528, 2024). "Results indicate that elevated levels of circulating inflammatory cytokines IL-2, IL-17, IL-18, and IFN-γ are related to enhanced risk of psoriasis and may help to predict clinical outcomes in individuals with psoriasis." (PMID 37883350, 2023). "Among them, IL-18 expression is significantly correlated with the severity of psoriasis." (PMID 36742336, 2023). "While IL-18 signaling exacerbates psoriasis pathology by inducing Th1 responses, IL-18Rα mediated pathway may have a regulatory role in neutrophil activation in psoriasis." (PMID 37964882, 2023). "Under Th1 conditions, IL-18 recruit dendritic cells to the inflammatory foci of psoriasis." (PMID 37964882, 2023). "Various cytokines and adhesion molecules, including interleukin (IL)-1, IL-2, IL-6, IL-8, IL-12, IL-18, TNF-α, and nerve growth factor, are abnormally expressed in the lesions of psoriasis patients, suggesting that psoriasis is associated with the release of NF-κB-regulated inflammatory cytokines." (PMID 36835162, 2023). "Deletion of IL-18 reduces psoriasis-like skin inflammation in mice." (PMID 37049538, 2023). "First evidence of a possible involvement of the inflammasome in psoriasis emerged more than twenty years ago, in which a dysregulation of IL-1 and increased protein expression of IL-18 in lesional skin of psoriasis patients compared to skin of healthy controls were detected." (PMID 37325658, 2023). "Many reports have focused on the significance of IL-18 in psoriasis." (PMID 36742296, 2023). "The results of this meta-analysis suggest that circulating levels of IL-2, IL-17, IL-18, and IFN-γ may serve as biomarkers of psoriasis risk." (PMID 37883350, 2023). "Similarly, in human studies, skin sections of psoriasis patients showed elevated levels of IL-18 and Caspase-1 compared to healthy subjects." (PMID 36032110, 2022). "Psoriasis was associated with IL-18 and E-selectin levels regardless of periodontal status, age, and smoking habit (p < 0.05)." (PMID 34685372, 2021). "However, more studies are still necessary to determine the role of IL-18 in periodontal tissue in psoriasis patients." (PMID 34685372, 2021). "Inflammasomes are high-molecular-weight protein complexes that may cleave the two main proinflammatory cytokines, pro-interleukin-1β and pro-interleukin-18, into active forms, and contribute to psoriasis." (PMID 34072753, 2021). "In addition, researchers revealed that the expression level of NLRP1 mRNA and circulating IL-18 is significantly increased in the peripheral blood of patients suffering from psoriasis." (PMID 34072753, 2021).
psoriasis (continued). "Altogether, these findings suggest that IL-18 could be a valuable biomarker for diagnosing and staging the severity of psoriasis." (PMID 34685372, 2021). "According to our results, the diagnosis of psoriasis demonstrated a significant influence on the GCF levels of IL-18 and sE-selectin (p < 0.05), whereas mild periodontitis of the explored variables affected the concentrations of sICAM-1 (p = 0.02, results not shown)." (PMID 34685372, 2021). "In addition, a positive correlation between the serum concentrations of IL-18 and psoriasis severity and activity has previously been reported, hinting at the prospective value of cytokine as an objective biomarker for the disease." (PMID 34685372, 2021). "We further explored whether the presence of psoriasis influenced the GCF levels of IL-18, sE-selectin, and sICAM-1 after adjusting for age, tobacco use, and periodontitis severity." (PMID 34685372, 2021). "sICAM-1 levels have been reported to positively correlate with IL-18 psoriasis severity; this suggests that IL-18 could be regulating the production of sICAM-1 in psoriasis patients." (PMID 34685372, 2021). "Thus, IL-18 and sE-selectin appear to be promising biomarkers for screening and diagnosis of psoriasis, helping clinicians make their early diagnosis." (PMID 34685372, 2021). "GCF levels of IL-18 were significantly higher in the psoriasis group versus controls (p < 0.05)." (PMID 34685372, 2021). "Thus, indicating that, as protein levels of ASC and IL-18 increase, so do the odds of a patient having psoriasis." (PMID 32903782, 2020). "In addition, levels of IL-18 have been previously shown to be elevated in the serum patients with psoriasis." (PMID 32903782, 2020). "Similarly, in our study, we found a statistically significant correlation between BDI scores and serum IL-18 concentrations in patients with psoriasis." (PMID 30092066, 2018). "Notably, patients with psoriasis have higher IL-18 concentrations in plasma than do healthy controls." (PMID 30092066, 2018). "The present meta-analysis found that TNF-α, IFN-γ, sE-selectin, IL-2, IL-6, IL-8, IL-18, IL-22, fibrinogen and C3 were elevated in serum of patients with psoriasis, indicating that serum levels of these cytokines may correlate to their levels in tissue." (PMID 29416693, 2018). "In our study, compared to controls, patients with psoriasis had significantly higher BMIs and concentrations of total cholesterol; moreover, they had significantly higher concentrations of pro-inflammatory cytokines IL-6 and IL-18." (PMID 30092066, 2018). "Therefore, suppression of the functions and expression of IL-18 is critical for the treatment of psoriasis." (PMID 26901187, 2016). "Notably, IL-18, which belongs to the IL-1 superfamily, is a representative proinflammatory cytokine that is highly expressed in psoriasis." (PMID 26901187, 2016). "Also, there is a significant negative correlation between the level of IL-18 and Erdr1 expression in lesional skin of psoriasis patients, implying opposing effects of IL-18 and Erdr1." (PMID 27823968, 2016). "A representative proinflammatory cytokine, IL-18, has been classified as a biomarker for the activity of psoriasis, in addition to other cytokines including transforming growth factor beta 1 (TGF-β1), tissue inhibitor of metalloproteinase 1 (TIMP-1), and matrix metalloproteinase 1 (MMP-1)." (PMID 26901187, 2016). "IL-18 may recruit dendritic cells expressing IL-18R to inflammatory areas under Th1 conditions, as in psoriasis." (PMID 26690141, 2015). "Moreover, serum levels of IL-18 positively correlate with the clinical severity score of skin lesions, as is observed with the psoriasis area and severity index (PASI), including chronic plaque-type psoriasis and generalized pustular psoriasis." (PMID 26690141, 2015). "IL-18 can be considered a biomarker for the severity of psoriasis." (PMID 26690141, 2015). "Psoriasis patients have increased expression of IL-18 in the skin tissue and blood." (PMID 26690141, 2015).